RALY (RALY heterogeneous nuclear ribonucleoprotein)
Diseases named in the same sentence as RALY in open-access papers (continued):
Sharing a sentence is not in itself a finding about the gene and the disease.
cancer (13 papers, 2011 to 2026). A tumor composed of atypical neoplastic, often pleomorphic cells that invade other tissues. "RALY overexpression inhibited the immune/inflammatory-related genes expression at transcription level might be associated with the chemo treatment resistance in cancer cell biological process." (PMID 35941292, 2022). "In CRC, mitochondrial metabolic reprogramming in cancer cells is inhibited by apoptosis caused by regulation of the RNA-binding protein RALY, while METTL3 can affect tumor development by targeting RALY." (PMID 39033180, 2024). "RALY is elevated in many cancer cells and participates in tumor progression through both proliferation and aggressive biological behaviors 11-13." (PMID 38993567, 2024). "The results revealed 910 RALY-regulated AS events in genes that were strongly enriched in transcription regulation and predicted a mechanism of RALY to deregulate the cancer cell transcriptome." (PMID 35941292, 2022). "Which data provides evidence for further investigation of the function of RALY in cancer immunology and clinical resistance in cancer advance under the given therapy." (PMID 35941292, 2022). "Further investigation of the role of all RALY proteins in carcinogenesis, especially in vivo and in vitro, will be more significant and preferred the new perspectives in cancer treatment." (PMID 35941292, 2022). "Analysis of RALY expression and survival in a number of cancers showed that the levels of RALY expression were dramatically decreased in cancer tissues compared with corresponding normal tissues RALY expression is related with prognosis in cancer patients." (PMID 35941292, 2022). "Quaking I-5 (QKI-5), RALY heterogeneous nuclear ribonucleoprotein (RALY), and KH-type splicing regulatory protein (KHSRP) promote cancer cell proliferation and invasion, and they are associated with OS probability in NSCLC." (PMID 36118863, 2022). "This founding widened our current knowledge of the critical role of RALY in regulating the immune/ inflammatory response in cancer." (PMID 35941292, 2022). "RALY is a multifunctional RNA-binding protein involved in cancer metastasis, prognosis, and chemotherapy resistance in various cancers." (PMID 35941292, 2022). "However, RALY selectively regulates the alternative splicing of transcription factors mainly associated with immune/inflammatory response and tumorigenesis in HeLa cells, which affect the cellular process, including proliferation and apoptosis, and metabolism in cancer cells." (PMID 35941292, 2022). "In recent years, studies on RALY in cancer have been increasing." (PMID 42100402, 2026). "Moreover, RALY modulates alternative splicing of mRNA, which leads to RNA complexity and protein diversity in cancer." (PMID 38993567, 2024). "Furthermore, the expression of one gene, RALY, showed an intimate correlation with gene amplification, promotor methylation, and mRNA level in the cancer database." (PMID 36428700, 2022). "Further studies are required to verify the molecular function of RALY in cancer metabolism." (PMID 35941292, 2022). "As an important member of the hnRNP family, RALY plays an important role in many processes of mRNA metabolism, such as mRNA splicing, stability, and the translational regulation of specific mRNAs in many different cell types, especially in cancer cells (32, –, 34)." (PMID 38323828, 2024). "Thus, targeting RALY degradation to inhibit cancer progression may be a new therapeutic strategy for HCC." (PMID 38993567, 2024). "The novel role of RALY in regulating immune/inflammatory gene expression may explain its function in regulating chemotherapy resistance and provides novel insights into further exploring the molecular mechanism of RALY in regulating cancer immunity and chemo/immune therapies." (PMID 35941292, 2022). "We further summarized six genes (IGF2BP3, LYAR, RALY, STAU1, SYNCRIP, and TOP1) that displayed high correlations between mRNA and protein expression in both cancer and cell line databases." (PMID 36428700, 2022).
cancer (continued). "With the assistance of RALY, PTBP1 can bind to the pre‐mRNA of DNMT3B and drive an oncogenic splicing switch in DNMT3B to produce DNMT3B‐L, which in turn induces promoter methylation of DUSP2, thereby increasing resistance of cancer cells to irradiation." (PMID 39287090, 2024). "Second, different proteoforms from the same cancer-related gene (e.g., DAP, CALM1, HDGF, JPT1, RALY, and NPM1) may have potentially varied biological functions in modulating CRC metastasis, because they show opposite expression profiles between the SW480 and SW620 cells." (PMID 36542699, 2022). "To determine whether YB-1, NONO, and RALY mRNA transcripts could also be increased in other cancer histotypes, we searched the PrognoScan database." (PMID 22118625, 2011).
tumor (9 papers, 2011 to 2026). "In addition, in vivo xenograft experiments showed that depletion of OGT reduced the tumor weight and volume caused by RALY overexpression." (PMID 38993567, 2024). "Using this model, we determined that RALY ablation led to lower liver-to-body weight ratios, fewer tumor numbers, and smaller tumor sizes." (PMID 38993567, 2024). "Loss-of-function assays reveal that O-GlcNAcylation is essential for the tumor- proliferative effect of RALY." (PMID 38993567, 2024). "RALY functions as a core regulator in tumorigenesis and tumor progression." (PMID 42100402, 2026). "In addition, the mRNA expression levels of RALY in 70 HB tissues were up-regulated compared with the paired non-tumor tissues." (PMID 31781561, 2019). "Mechanistically, ZFAS1 functions as a competitive endogenous RNA (ceRNA) that sequesters tumor-suppressive miRNAs including miR-150 and miR-193a-3p, thereby de-repressing downstream oncogenic targets such as ZEB1/MMP14 and RALY/HGF/c-Met." (PMID 41450817, 2026). "Remarkably, the combined knockdown of UBA2, RALY, and FOXD1 resulted in the smallest tumor volumes and the longest survivals of nude mice in vivo." (PMID 37906341, 2023). "Remarkably, the combined knockdown of UBA2, RALY, and FOXD1 largely suppressed xenograft tumor growth and VM and prolonged nude mice survival." (PMID 37906341, 2023). "Collectively, these results indicate that RALY is identified as an oncogene in HCC but its abnormal expression and tumor-promoting mechanisms are still unknown." (PMID 38993567, 2024). "However, there still are several limitations, such as the development of brain penetrant inhibitors of UBA2, RALY, FOXD1, and DKK1 that can be selective against tumor cells as well as more studies for clinical research." (PMID 37906341, 2023). "The results showed that ASEs up-regulated in BLCA with high-level neoplasm grade were enriched to several RBPs’ motifs, including “poly-T” motifs and polypyrimidine tract (Py-tract) sequence of HuR, CPEB4, TIA1, HNRNPC, PTBP1, RALY and ZC3H14, and motifs of PCBP2 and SNRNP70." (PMID 37810965, 2023). "Moreover, the combined knockdown of UBA2, RALY, and FOXD1 resulted in the smallest tumor volume." (PMID 37906341, 2023).
infection (2 papers, 2022 to 2024). The state of being infected such as from the introduction of a foreign agent such as serum, vaccine, antigenic substance or organism. "Here, we revealed that PEDV infection inhibited endogenous RALY expression in host cells, and overexpression of RALY suppressed PEDV replication at various time points or infection stages in Vero and LLC-PK1 cells." (PMID 35753351, 2022). "Given the inhibitory effect of RALY on FMDV IRES-driven translation by blocking the formation of 80S ribosome, we analyzed the function of RALY in the switch between the translation and replication during the FMDV infection." (PMID 38323828, 2024).
blood disorders (1 paper, 2025). "Furthermore, four genes–UQCRFS1, PTPN6, RALY and ZMYM4–were identified for their associations with traits such as aging, forebrain and nervous system morphology, lung and bone morphology, neurodegenerative diseases and blood disorders." (PMID 40656995, 2025).
RALY also shares sentences with these, for which no sentence is quoted: anxiety disorder (1 paper); head and neck cancer (1); Hepatic steatosis (1); hepatoblastoma (1); laryngeal carcinoma (1); liver cancer (1); lung adenocarcinoma (1); multiple myelomas (1); neurodegenerative disease (1); nevus (1); Obesity (1); Thrombophlebitis (1).